SPINT1 (serine peptidase inhibitor, Kunitz type 1)
Diseases named in the same sentence as SPINT1 in open-access papers (continued):
Sharing a sentence is not in itself a finding about the gene and the disease.
tumor (continued). "The manuscript addressed on the regulatory relationship and tumor prognostic value of transcription factors (TFs) MACC1 and transmembrane protein SPINT1." (PMID 33751856, 2021). "SPDEF, TRIM3, HSPB1, SPINT1, EPN3, and LRFN2 were significantly highly expressed in the HER2-positive type than in TNBC (p < 0.05), as the HER2-positive type is reported to have a larger tumor size and higher stage." (PMID 36428562, 2022). "Our results show that genetic alterations of SPINT1 correlated with a poor prognosis of SKCM patients and provide evidence that SPINT1 expression positively correlated with tumor macrophage infiltration, but not neutrophils." (PMID 31519199, 2019). "In addition, a positive correlation of both inflammation and macrophage marker with SPINT1 levels was found in tumor samples, fitting the increased number of TAM in SKCM with high SPINT1 levels." (PMID 31519199, 2019). "Importantly, independent research discovered an interaction between Spint1 and membrane-bound serine proteinases to support EMT transitions, and inhibition of Spint1 was shown to be of therapeutic benefit by increasing tumor specific immune responses." (PMID 29254206, 2017). "Thus, because Spint1 and Spint2 serve to inhibit the activity of HGF, these genes have been characterised as tumour suppressors." (PMID 18506145, 2008). "This is an interesting observation, since SPINT1 is a membrane-bound protein that may, therefore, inhibit their targets in both tumor cell autonomous and non-autonomous manners." (PMID 31519199, 2019). "Another interesting observation is that SPINT1 transcript levels positively correlated with macrophage infiltration, but not neutrophil one, in SKCM tumor samples." (PMID 31519199, 2019).
infection (6 papers, 2013 to 2022). The state of being infected such as from the introduction of a foreign agent such as serum, vaccine, antigenic substance or organism. "Relative concentrations of the attachment receptor, ACE2, MASPs, their endogenous inhibitors (the Kunitz-type transmembrane inhibitors, HAI-1/SPINT1 and HAI-2/SPINT2, as well as major circulating serpins) would determine the infection rate of host cells." (PMID 33268377, 2021).
SPINT1 also shares sentences with these, for which no sentence is quoted: bladder cancer (5 papers); ovarian carcinoma (4); adenoma (3); endometrial cancer (3); lung adenocarcinoma (3); renal cell carcinoma (3); Burkitt lymphoma (2); cervical cancer (2); glioblastoma (2); hematological cancer (2); hepatocellular carcinoma (2); multiple myeloma (2); oral squamous cell carcinoma (2); pancreatic ductal adenocarcinoma (2); alcoholic hepatitis (1); Alzheimer disease (1); anemia (1); B cell lymphomas (1); benign prostatic hyperplasia (1); brain diseases (1); brain glioma (1); chronic lymphocytic leukemia (1); Cirrhosis (1); cognitive decline (1); colorectal adenocarcinoma (1); dysplasia (1); endothelial dysfunction (1); Hepatic fibrosis (1); hypertrophic cardiomyopathy (1); ichthyosis (1).
A further 21 diseases each share a sentence with SPINT1 in 1 paper.